TRPV3 (transient receptor potential cation channel subfamily V member 3)
Diseases named in the same sentence as TRPV3 in open-access papers (continued):
Sharing a sentence is not in itself a finding about the gene and the disease.
cardiac hypertrophy (continued). "Our studies revealed a novel hypertrophic signalling pathway (miR‐103/TRPV3/autophagy), and manipulation of this signalling axis may provide innovative approaches to prevent cardiac hypertrophy." (PMID 30604587, 2019). "In summary, our study established that TRPV3 was activated by hypertrophic stimulus, and intracellular calcium concentration was increased, which in turn activated calcineurin/NFATc3 pathway, and eventually led to cardiac hypertrophy." (PMID 30299584, 2018). "Our results indicated that cardiac hypertrophy was alleviated by silencing TRPV3." (PMID 30299584, 2018). "Firstly, a significant finding of this study was that the specific TRPV3 expression was increased in pathological cardiac hypertrophy induced by abdominal aortic constriction and Ang II stimulation under the increase in cardiac‐specific BNP and β‐MHC, not in swimming exercise model." (PMID 30299584, 2018). "Firstly, we would confirm whether TRPV3 was involved in the regulation of cardiac hypertrophy." (PMID 30604587, 2019). "Hence, we conjectured that TRPV3 channel might participate in cardiac hypertrophy by regulating the autophagy pathway." (PMID 30604587, 2019). "Therefore, we speculate that the activation of TRPV3 channels can increase the intracellular calcium concentration, and thus promote myocardial cell autophagy, ultimately leading to cardiac hypertrophy." (PMID 30604587, 2019). "Therefore, we speculated that the TRPV3 could be directly or indirectly involved in cardiac hypertrophy." (PMID 30299584, 2018). "However, the effects and mechanisms of TRPV3 on cardiac hypertrophy need to be further explored." (PMID 30299584, 2018). "Transient receptor potential vanilloid 3 (TRPV3) is a member of TRP, however, the functional role of TRPV3 in cardiac hypertrophy remains unclear." (PMID 30299584, 2018). "The present work indicated that enhancive TRPV3 was specific in pathological cardiac hypertrophy, not in physiological cardiac hypertrophy." (PMID 30299584, 2018). "TRPV3 was elevated in pathological cardiac hypertrophy, but not in swimming exercise‐induced physiological cardiac hypertrophy in rats." (PMID 30299584, 2018). "This novel finding indicated the TRPV3 might play a role in pathological, but not physiological myocardial hypertrophy." (PMID 34867442, 2021).
non-small cell lung carcinoma (5 papers, 2016 to 2025). A group of at least three distinct histological types of lung cancer, including non-small cell squamous cell carcinoma, adenocarcinoma, and large cell carcinoma. "Overexpression of TRPV3 correlates with tumor progression and short OS in non-small cell lung carcinoma (NSCLC) (p = 0.020); and loss or reduction of TRPML1 mRNA expression correlates with short survival in glioblastoma (GBM) patients (p < 0.0298)." (PMID 31801263, 2019). "Studies have shown that in renal clear cell carcinoma and non-small cell lung cancer, the high expression of TRPV3 is significantly correlated with increased tumor grade and poor prognosis." (PMID 41331166, 2025). "Another study found that TRPV3 facilitated angiogenesis via the HIF-1α-VEGF signaling pathway in non-small-cell lung cancer." (PMID 39469202, 2024). "The protein expression of TRPV3 in non-small cell lung cancer and its relationship with clinicopathological factors have not yet been examined." (PMID 27023518, 2016).
alopecia (3 papers, 2018 to 2025). Hair loss usually from the scalp. "Overactive TRPV3 in rodents induces phenotypes akin to AD and alopecia." (PMID 40409547, 2025).
breast carcinoma (3 papers, 2022 to 2024). "It has been reported that the high expression of TRPV3 will cause pain in pancreatic cancer, bone cancer and breast cancer." (PMID 36677834, 2023). "Next, we will conduct experiments on animals to continue to observe the effect of TRPV3 on breast cancer." (PMID 38706904, 2024). "Then, we tested the expression level of TRPV3 in several breast cancer cell lines (MCF-7, SK-BR3, MDA-MB-468, MDA-MB-231)." (PMID 38706904, 2024). "In order to determine the mechanism of TRPV3 mediated migration, proliferation and apoptosis of breast cancer cells, we identified EGFR as a key mediator." (PMID 38706904, 2024). "Collect animal samples for transcriptomics or proteomics detection, and further study the deeper mechanism of TRPV3 regulating breast cancer through experiments." (PMID 38706904, 2024). "Our results collectively suggest that TRPV3 siRNA inhibits migration and proliferation, and promoted apoptosis in breast cancer cells by EGFR/AKT pathway." (PMID 38706904, 2024). "In this study, we studied the intracellular levels of Ca2+ by Carvacrol or TRPV3 siRNA in breast cancer cells." (PMID 38706904, 2024). "Patients often experience pain before breast cancer surgery, and there is evidence that this pain is due to the high expression of TRPV3." (PMID 36677834, 2023). "In conclusion, these results suggest that TRPV3 siRNA may play a role as a tumor inhibitory tool by inhibiting cell migration and proliferation, and promoting apoptosis in breast cancer cells." (PMID 38706904, 2024). "TRPV3 inhibition (TRPV3 siRNA) exert its pro-apoptotic activity (the number of apoptotic positive cells and caspase-3 activity were remarkably increased), anti-migration and anti-proliferation, and cell viability decreased in breast cancer cells." (PMID 38706904, 2024). "TRPV3 was significantly increased in breast cancer specimens." (PMID 38706904, 2024). "Moreover, the TUNEL revealed that the number of apoptotic positive cells was increased in cultured breast cancer cells transfected with TRPV3 siRNA." (PMID 38706904, 2024). "The results showed that the overexpression of TRPV3 might play an important role in the process of breast cancer delivery." (PMID 38706904, 2024). "Carvacrol stimulated the increase of intracellular Ca2+concentration, but was inactive in stimulating Ca2+ by TRPV3 siRNA in breast cancer cells, demonstrating the opposite effect of Carvacrol and TRPV3 siRNA in BC progression (migration, proliferation and apoptosis)." (PMID 38706904, 2024). "In this study, we found that TRPV3 significantly up-regulation in breast cancer and MCF-7 cells." (PMID 38706904, 2024). "We observed that TRPV3 upregulated in human breast cancer samples and cell lines." (PMID 38706904, 2024). "Here, we explored the effect of TRPV3 on breast cancer cells and its potential mechanism." (PMID 38706904, 2024). "It is currently unclear whether TRPV3 regulates the progress of breast cancer through EGFR pathway." (PMID 38706904, 2024). "Although TRPV3 is a member of TRP superfamily, through network analysis, TRPV3 related to epithelial mesenchymal transformation of breast cancer 8, but the role and mechanism of TRPV3 in breast cancer have not fully clarified." (PMID 38706904, 2024).
hearing loss (3 papers, 2019 to 2025). "FPP is an endogenous activator of transient receptor potential cation channel, vanilloid type (TRPV) 3, and TRPV3 deficiency protects against kanamycin-induced hearing loss." (PMID 32765216, 2020). "Based on these observations, it was suggested that TRPV3 and TRPV4 play an important role in neuroprotection while TRPV1 and TRPV2 are involved in the pathology of hearing loss." (PMID 31866822, 2019).
osteoarthritis (3 papers, 2023 to 2025). A noninflammatory degenerative joint disease occurring chiefly in older persons, characterized by degeneration of the articular cartilage, hypertrophy of bone at the margins and changes in the synovial membrane. "Measurements of iNOS and COX-2, mRNA and protein levels, were also conducted using qRT-PCR and western blotting, respectively, to ascertain the impact of TRPV3 knockdown on osteoarthritis inflammation." (PMID 40166423, 2025). "Here, we aimed to understand the regulatory role and effect of TRPV3 on apoptosis and inflammation in osteoarthritis by using C28/I2 chondrocyte cells as a model." (PMID 40166423, 2025). "We hypothesized that the knockdown of TRPV3 may mitigate the effects induced by IL-1β in patients with osteoarthritis." (PMID 40166423, 2025). "Although preclinical studies suggest a role for TRPV3 in skin diseases, to date, only the TRPV3 inhibitor, GRC15300 (SAR292833), by Glenmark Pharmaceuticals has progressed to clinical trials for targeting osteoarthritis and neuropathic pain." (PMID 41118703, 2025). "We assessed the impact of TRPV3 downregulation on inflammatory mediators, including iNOS and COX-2, in IL-1β-stimulated chondrocytes, as their dysregulation contributes to the pathobiology of osteoarthritis." (PMID 40166423, 2025).
cerebral palsy (2 papers, 2025). A group of disorders affecting the development of movement and posture, often accompanied by disturbances of sensation, perception, cognition, and behavior. "Here, we report a 17-year-old male of Asian descent, with cerebral palsy and intellectual disability, but without any dermatologic features typically associated with OS, despite carrying a TRPV3 variant." (PMID 40124882, 2025). "Our case expands the understanding of TRPV3 variants, emphasizing the importance of considering genetic testing in patients with intellectual disability and cerebral palsy, even without skin manifestations." (PMID 40124882, 2025).
clear cell renal cell carcinoma (2 papers, 2023 to 2025). "In renal clear cell carcinoma, TRPV3 can induce the expression of immune checkpoints such as LAG3, CTLA4, PDCD1, and TIGIT, leading to the accumulation of immunosuppressive T cells in the tumor microenvironment." (PMID 41331166, 2025). "TRPV3 is the most significant predictive predictor of clear cell renal cell carcinoma among these several other markers." (PMID 37344882, 2023). "As a consequence of this, the TRPV family, and specifically TRPV3, can serve as a predictive biomarker in clear cell renal cell carcinoma to identify both the patient's prognosis and the degree to which immune cells have been infiltrated." (PMID 37344882, 2023).
fibrosis (2 papers, 2020 to 2025). the formation of excess fibrous connective tissue in an organ or tissue in a reparative or reactive process. "Among the genes linked to hypermethylation in the cases, TRPV3,37DCP2,38KCNIP4,39 and ARRB140 have been associated with progression of liver disease to fibrosis and cirrhosis." (PMID 40275933, 2025). "TRPV3 channel induces dermal fibrosis via the TRPV3/TSLP/ mothers against decapentaplegic homolog 2/3 (Smad2/3) pathways in dermal fibroblasts." (PMID 32485929, 2020).
melanoma (2 papers, 2019 to 2025). A malignant, usually aggressive tumor composed of atypical, neoplastic melanocytes. "Altered TRPV3 expression levels have been reported in several malignancies, including non-small cell lung cancer, melanoma, squamous cell carcinoma, and breast cancer." (PMID 40869148, 2025). "Meanwhile, 2-APB, an activator of TRPV2 (also activates TRPV1 and TRPV3 but does not affect TRPV4), clearly attenuated the proliferation of A2058 melanoma cells (IC50 = 150 μM)." (PMID 30881453, 2019).
myocardial infarction (2 papers, 2021 to 2023). Gross necrosis of the myocardium, as a result of interruption of the blood supply to the area, as in coronary thrombosis. "Hypoxia-induced apoptosis and inflammation are important causes of cardiovascular diseases such as myocardial infarction (MI), and TRPV3 siRNA can protect the cardiomyocytes from hypoxia-induced apoptosis and inflammation." (PMID 36677834, 2023). "One very recent study found that TRPV3 is upregulated after myocardial infarction in rats and that miR-369, a microRNA regulating cardiac fibrosis, is downregulated." (PMID 34867442, 2021).
Obesity (2 papers, 2019 to 2021). Accumulation of substantial excess body fat. "Besides, berberine alleviates olanzapine-induced obesity by targeting TRPV1/TRPV3 in hypothalamus of mice." (PMID 34249940, 2021). "However, the expression of TRPV3 and its role in human obesity needs further exploration." (PMID 34249940, 2021). "The expression of TRPV3 was dramatically down-regulated in visceral adipose tissue of obesity mice, including HFD-induced obesity mice, ob/ob and db/db mice." (PMID 34249940, 2021). "TRPV3 could form heteromeric channels with TRPV1, which also involves in the regulation of adipogenesis and HFD-induced obesity." (PMID 34249940, 2021).
pterygium (2 papers, 2021 to 2022). A wedge-shaped fibrovascular lesion arising from the bulbar conjunctiva and extending to the cornea. "Significantly, TRPV3, which causes a form of the disease known as Olmstead Syndrome, was also strikingly upregulated in both pterygium and pinguecula." (PMID 34769520, 2021). "Significantly, TRPV3, which causes a form of the disease known as Olmstead Syndrome, was also highly upregulated in both pterygium, and moderately so in pinguecula." (PMID 34769520, 2021). "This suggests that TRPV3 expression could contribute to the proliferative and inflammatory phenotype we observed in our pterygium and pinguecula specimens." (PMID 34769520, 2021).
Stroke (2 papers, 2025). Sudden impairment of blood flow to a part of the brain due to occlusion or rupture of an artery to the brain. "Blocking TRPV3 or TRPM2 shows potential for reducing brain damage and improving stroke outcomes, an effect potentially linked to modulation of γδ T cell activity." (PMID 40746532, 2025). "Additionally, consistent with the idea that ischemic injury upregulates TRPV3 expression, leading to intracellular Ca2+ overload and progressive cell death, inhibition of TRPV3, rather than N-methyl-D-aspartate (NMDA) receptors, protected against progressive cell death after stroke." (PMID 41279562, 2025).
ulcerative colitis (2 papers, 2018 to 2020). An inflammatory bowel disease involving the mucosal surface of the large intestine and rectum. "TRPV3 levels were slightly decreased in patients with ulcerative colitis in this study." (PMID 29914124, 2018). "The aim of this study was to evaluate the expression levels of TRPV1, TRPV2, TRPV3 and TRPV4 in mucosa epithelial cells of colonic biopsies from patients with ulcerative colitis (UC) in comparison to colonic resections from non-IBD patients (control group)." (PMID 29914124, 2018).
allergic rhinitis (1 paper, 2010). Inflammation of the nasal mucous membranes caused by an IgE-mediated response to external allergens. "Consequently, it has been suggested that TRPV3 acts as a chemoesthetic receptor and is also involved in allergic rhinitis caused by repeated exposures to certain odors." (PMID 20586674, 2010).
Arthritis (1 paper, 2009). Inflammation of a joint. "A gain-of-function mutation of TRPV3 as well as the number of mast cells and T cells with TCRVβ8S2 may be needed for the development of AD, and a high number of mast cells may play an important role in the development of arthritis." (PMID 19463197, 2009).
asthma (1 paper, 2024). "The role of the other subfamilies of TPRV in VILI still needs to be elucidated and might be promising because they are reportedly involved in ovalbumin-induced asthma models (TRPV1, TRPV2, TRPV5), and lung epithelial injury caused by cigarette smoke, LPS, seawater inhalation and wood smoke (TRPV3)." (PMID 39664395, 2024).
Autoimmunity (1 paper, 2013). The occurrence of an immune reaction against the organism's own cells or tissues. "It is therefore possible that mutations causing constitutive activation of TRPV3 may also alter the properties of Langerhans cells by impeding dermatological tolerance and driving local autoimmunity." (PMID 23692804, 2013).
bladder cancer (1 paper, 2025). "Cholesterol supplementation further enhanced TRPV3 activity in KU-19-19 cells, a finding of potential relevance given the known dysregulation of cholesterol metabolism in bladder cancer." (PMID 41422779, 2025). "TRPV3 activation in the KU-19-19 bladder cancer cells stimulated ATP release, which was abolished by pharmacological TRPV3 blockade, confirming target specificity." (PMID 41422779, 2025). "In this study, TRPV3 was identified in human bladder cancer cell lines, and its functional activation was demonstrated, using a novel small-molecule agonist activator of TRPV3 channel 1 (AV3-1), discovered through medium-throughput screening." (PMID 41422779, 2025). "Using AV3-1, this study demonstrates TRPV3 expression in bladder cancer cells." (PMID 41422779, 2025).
cervical adenocarcinoma (1 paper, 2022). An adenocarcinoma arising from the cervical epithelium. "Interestingly, TRPM4 showed higher expression only in cervical adenocarcinoma; while TRPV3 showed lower expression only in cervical adenocarcinoma." (PMID 36072430, 2022).
channelopathy (1 paper, 2025). Channelopathies are a group of diseases caused by the dysfunction of ion channel subunits or their interacting proteins. "Given the close association between TRPV3 channelopathy and AD, our finding for the role of ROSA in selective inhibition of TRPV3 has enriched the NF-κB signaling pathway as a downstream regulator of TRPV3, which is involved in regulating Car-induced skin inflammatory responses." (PMID 40409547, 2025).
colitis (1 paper, 2018). Inflammation of the colon. "Other genes within our top down-regulated DEG list including Sycn, Trpv3, Hpgd, and Fam134b are also found down-regulated in DSS colitis or CRC, suggesting that their decreased expression is a common feature during intestinal tissue damage and inflammation." (PMID 29339782, 2018).
colonic adenocarcinoma (1 paper, 2023). "In a study of 93 patients, decreased TRPV3 and TRPV4 mRNA was found in colonic adenocarcinoma compared to normal tissue." (PMID 37240443, 2023).
Dry skin (1 paper, 2021). Skin characterized by the lack of natural or normal moisture. "Previous studies have demonstrated that protease-activated receptor 2 (PAR2), TRPV3, and TRPV4, are involved in the production of TSLP in keratinocytes under dry skin conditions." (PMID 34925342, 2021).
epilepsy (1 paper, 2022). A brain disorder characterized by episodes of abnormally increased neuronal discharge resulting in transient episodes of sensory or motor neurological dysfunction, or psychic dysfunction. "Of the 30 protein coding genes with identified coding sequence or expression differences, ten had a prior association with seizure or epilepsy based on literature and database searches, including Aspa, Hic1, Nlrp1a, Nlrp1b, Pafah1b1, Smg6, Trpv1, Trpv3, Ywhae and 6330403K07Rik." (PMID 35606653, 2022).
esophageal squamous cell carcinoma (1 paper, 2019). Esophageal squamous cell carcinoma (ESCC) is a type of esophageal carcinoma (EC) that can affect any part of the esophagus, but is usually located in the upper or middle third. "We found that TRPV‐1, 2, and 4 were all expressed at both mRNA and protein levels in the nontumor esophageal squamous cells and esophageal squamous cell carcinoma cells, whereas TRPV3 mRNA transcript and protein were not detectable among all 3 cell lines." (PMID 30761248, 2019).
familial episodic pain syndrome (1 paper, 2025). "Notably, the S4-S5 linker appears to be a hot-spot for mutations in several TRP channels, including TRPV3 (congenital Olmsted syndrome), TRPV4 (skeletal dysplasia, motor/sensory neuropathies), TRPA1 (familial episodic pain syndrome), and TRPML1 (mucolipidosis type IV)." (PMID 41005473, 2025).
Ht (1 paper, 2023). "Studies on hairless mice with TRPV3 gain-of-function mutations (G573C in WBN/Kob-Ht and G573S in DS-Nh mice) have highlighted the relevance of TRPV3 in both normal and abnormal skin conditions." (PMID 37629111, 2023).
inflammatory bowel disease (1 paper, 2021). A spectrum of small and large bowel inflammatory diseases of unknown etiology. "Transient receptor potential vanilloid-3 (TRPV3) and transient receptor potential vanilloid-type 4 (TRPV4) are indirectly involved in gastrointestinal inflammation from inflammatory bowel diseases because they function as sensors of harmless and non-harmless chemical or physical stimuli." (PMID 34834237, 2021).